ODAM (odontogenic, ameloblast associated)
Diseases named in the same sentence as ODAM in open-access papers:
ODAM is named in the same sentence as 31 diseases in open-access papers, as found by Europe PMC text mining. Sharing a sentence is not in itself a finding about the gene and the disease. The quoted sentences say what the papers report.
breast carcinoma (5 papers, 2013 to 2022). "The apparent anti-neoplastic effects of ODAM in cultured melanoma and breast cancer cells are associated with increased PTEN expression, and suppression of AKT activity." (PMID 23648148, 2013). "Prior retrospective studies of breast cancer patient biopsies indicated an increase in ODAM expression localized to the cell nucleus associated with advancing disease stage, yet this expression corresponded with improved survival for patients at each stage." (PMID 23648148, 2013). "The apparent association of ODAM expression with disease status in breast cancer and melanoma, and the inhibition of neoplastic and metastatic properties shown in ODAM-transfected breast tumor cells have led us to investigate the role of this protein in the tumorigenesis of melanoma." (PMID 23648148, 2013). "The most significant finding in our studies is the marked suppression of AKT phosphorylation/activation upon ectopic ODAM expression in both melanoma and breast cancer cell lines." (PMID 23648148, 2013). "This suggests that ODAM has a potentially significant role in regulating tumorigenesis and metastasis in breast cancer with possible clinical implications." (PMID 23648148, 2013). "Our previous studies indicated that ectopic ODAM expression in MDA-MB-231 breast cancer cells led to suppression of tumorigenic properties in vitro and in murine tumor models." (PMID 23648148, 2013). "Similar to our earlier studies with breast cancer cells, the results indicate that ODAM expression inhibits cell growth and migration in melanoma cells." (PMID 23648148, 2013). "Transfection of ODAM into breast cancer cells yields suppression of cellular growth, motility, and in vivo tumorigenicity." (PMID 23648148, 2013). "Moreover, upregulated ODAM expression was found to inhibit the neoplastic properties of breast cancer cells, suggesting its potential clinical importance for tumour therapy." (PMID 36117697, 2022). "Whilst further research indicated ODAM expression could be a predictive marker of breast cancer survival." (PMID 36117697, 2022). "ODAM protein was detected in sera from late-stage breast cancer patients." (PMID 25911094, 2015). "ODAM has further been found in other types of lung and breast tumors of epithelial origin and has been suggested as a prognostic marker for such neoplasms, particularly human breast cancer." (PMID 25309457, 2014). "In breast cancer patient biopsies a correlation was observed between ODAM expression/localization and disease staging/clinical outcome, indicating that ODAM may serve as a novel prognostic biomarker in this type of cancer." (PMID 23648148, 2013). "The Odontogenic Ameloblast-associated Protein (ODAM) is expressed in a wide range of normal epithelial, and neoplastic tissues, and we have posited that ODAM serves as a novel prognostic biomarker for breast cancer and melanoma." (PMID 23648148, 2013). "ODAM protein expression has been demonstrated in a wide range of normal odontogenic, glandular, and epithelial renewal tissues as well as in malignancies including odontogenic tumors, gastric cancer, breast cancer, lung cancer, and melanoma." (PMID 23648148, 2013).
periodontal disease (5 papers, 2015 to 2024). "Using dual aptamers has also been reported in the development of a sensor for odontogenic ameloblast-associated protein (ODAM), a periodontal disease biomarker in gingival crevicular fluid (GCF)." (PMID 37232930, 2023). "Understanding the role of ODAM will facilitate the regeneration of impaired JE, which is highly important to the treatment of periodontal diseases." (PMID 36117697, 2022). "Here we review the molecular structure, expression, and role of ODAM in odontogenesis, regeneration of JE, and periodontal diseases." (PMID 36117697, 2022). "Additional findings from an Odam knockout (KO) mouse model replicated structural changes observed during human periodontal disease, suggesting that ODAM is involved in the maintenance of periodontal structural integrity." (PMID 36117697, 2022). "To date, the role of ODAM in the pathological process of periodontal diseases remains to be fully elucidated." (PMID 36117697, 2022). "Significance: We investigate ODAM function during JE development and regeneration and its functional significance in the initiation and progression of periodontal disease." (PMID 25911094, 2015). "In addition, we evaluated ODAM protein levels in GCF from periodontitis and peri-implantitis patients for early diagnosis and progress monitoring of periodontal disease." (PMID 25911094, 2015).
periodontitis (5 papers, 2015 to 2023). An acute or chronic inflammatory process that affects the tissues that surround and support the teeth. "Odontogenic Ameloblast-Associated Protein (ODAM) in gingival crevicular fluid (GCF) can provide evidence of the detachment of junctional epithelium from the tooth surface by periodontitis." (PMID 30143043, 2018). "The comparison of periodontitis target proteins galactin-10, ODAM, and azurocidin proposed in other studies found that the difference in DEFA-1 levels was the largest between healthy and periodontitis GCF, and periodontitis was more effectively distinguished." (PMID 37443537, 2023). "Recently, they also reported that the expression of ODAM was increased not only at the early stage but also at the following stages in the inflammatory JE on gingival biopsy from an experimental periodontitis model induced by P. gingivalis." (PMID 30143043, 2018). "ODAM is involved in the adhesion of the JE to the tooth surface and is released into the gingival crevice when the adhesion is broken by progress into periodontitis." (PMID 30143043, 2018). "ODAM expression was reduced in the JE of experimental periodontitis by drugs, dextran sulfate sodium or periodontopathic bacteria (Porphyromonas gingivalis) compared with the sham group." (PMID 30143043, 2018). "Similar to periodontitis, the ODAM protein level was also increased significantly in GCF from peri-implantitis patients compared with healthy teeth and healthy implants." (PMID 25911094, 2015). "New findings presented in this paper demonstrate that ODAM functions during JE development and regeneration as well as its functional significance in the initiation and progression of periodontitis and peri-implantitis." (PMID 25911094, 2015). "On the basis of these findings, we investigated the expression of ODAM in GCF from periodontitis and peri-implantitis patients by ELISA." (PMID 25911094, 2015). "We investigated ODAM function during JE development and regeneration and its functional significance in the initiation and progression of periodontitis and peri-implantitis." (PMID 25911094, 2015). "It was enough to confirm the possibility of ODAM as a site-specific biomarker for periodontitis." (PMID 30143043, 2018). "Based on the potential of ODAM as a predictive marker for the diagnosis of subjects (using saliva) and sites (using GCF) at risk for periodontitis, development of point-of-care diagnostic tools can help to overcome the limitations of current clinical diagnostics." (PMID 30143043, 2018). "The levels of FDCSP and ODAM mRNA appear to be increased in periodontitis." (PMID 28560203, 2017). "In addition, the ODAM protein was expressed in GCF from periodontitis and peri-implantitis patients and correlated with probing depth in periodontitis patients." (PMID 25911094, 2015). "To investigate whether periodontitis affects ODAM expression in human JE, we immunohistochemically evaluated ODAM protein expression in a human tooth extracted because of severe periodontitis." (PMID 25911094, 2015). "Furthermore, the level of ODAM protein in GCF correlated with the probing depth in periodontitis patients." (PMID 25911094, 2015). "Therefore, we propose that ODAM in GCF could be used as a protein biomarker for periodontitis and peri-implantitis diagnosis." (PMID 25911094, 2015). "In previous study, we reported that odontogenic ameloblast-associated protein (ODAM) was extruded from the JE following the onset of JE attachment loss and was detected in gingival crevicular fluid (GCF), and proposed that ODAM could be used as a biomarker of periodontitis and peri-implantitis." (PMID 30143043, 2018). "ODAM participates in maintaining the integrity and homeostasis of the JE and PDL during the early stages of periodontitis." (PMID 28560203, 2017).
periodontitis (continued). "It is not readily explained that ODAM, which was not expressed or expressed at low levels in the JE of gingival biopsies from periodontitis patients, was detected at relatively high levels in the GCF from sites with deep pockets." (PMID 30143043, 2018). "As expected, the level of ODAM protein was increased significantly in GCF from periodontitis patients compared with healthy teeth without inflammation." (PMID 25911094, 2015). "Therefore, progression of periodontitis induces the expression of FDCSP and ODAM." (PMID 28560203, 2017).
colorectal cancer (3 papers, 2017 to 2024). A primary or metastatic malignant neoplasm that affects the colon or rectum. "ODAM expression level was found to be suggestive of the onset and patient prognosis of colorectal carcinoma (CRC), which was also associated with upregulation of PTEN and inactivation of AKT signalling." (PMID 36117697, 2022). "This was consistent with a previous report that down-regulation of ODAM is correlated with decreased overall survival in colorectal cancer since ODAM plays a protective role by inhibiting cells proliferation and metastasis in CRC." (PMID 28537885, 2017). "ODAM inhibits colorectal cancer growth by promoting PTEN and suppressing the PI3K/AKT pathway." (PMID 38572434, 2024).
ameloblastoma (2 papers, 2024 to 2025). The most common odontogenic tumor, arising from the epithelial component of the embryonic tooth and usually affecting the molar-ramus region of the mandible or maxilla. "In conclusion, our study demonstrates similarities in AMELX and ODAM expression between craniopharyngioma and ameloblastoma, supporting their shared embryological origins." (PMID 39451638, 2024). "The immunohistochemical analysis of AMELX, ODAM, and CK19 across the 44 cases revealed distinct expression patterns between craniopharyngioma and ameloblastoma." (PMID 39451638, 2024). "ODAM expression also did not significantly differ between craniopharyngioma and ameloblastoma (p = 0.209), with the majority of cases showing strong positive expression (+3)." (PMID 39451638, 2024). "In summary, while amelogenin and ODAM expression did not significantly differ between craniopharyngioma and ameloblastoma, CK19 expression was significantly higher in craniopharyngioma." (PMID 39451638, 2024).
melanoma (2 papers, 2013 to 2022). A malignant, usually aggressive tumor composed of atypical, neoplastic melanocytes. "When the A375 and C8161 human melanoma cell lines were transfected with a gene construct encoding ODAM, their cellular properties were affected in a fashion similar to our studies in MDA-MB-231 cells." (PMID 23648148, 2013). "Our studies demonstrate that ectopic ODAM expression in melanoma cell lines suppresses growth and migratory activity in these cells, while eliciting elevated PTEN expression and suppression of AKT activity." (PMID 23648148, 2013). "More recently, a retrospective study of melanoma patient samples have demonstrated a significant correlation of ODAM expression/nuclear localization and sentinel lymph node metastases indicative of poorer prognosis." (PMID 23648148, 2013). "Correspondingly, examination of the migratory abilities of the ODAM-expressing melanoma cell lines in transwell migration assays demonstrated that cell motility is strongly inhibited (70-80%) by ODAM expression in both A375 and C8161 melanoma cell lines." (PMID 23648148, 2013). "Given the evidence that ODAM is expressed in melanoma and corresponds with lymph node metastasis, we wished to examine the effects of ODAM expression on melanoma cell lines." (PMID 23648148, 2013). "In each of the melanoma cell lines the increase in PTEN subsequent to ODAM expression was sufficient that AKT activation was profoundly inhibited, and was recovered upon specific silencing of PTEN expression." (PMID 23648148, 2013). "A recent study of melanoma patient specimens indicated that nuclear ODAM-expression correlates with sentinel lymph node metastasis in over 70% of cases, indicative of higher stage melanoma at diagnosis and poor prognosis requiring more aggressive therapeutic intervention." (PMID 23648148, 2013). "In contrast to our observations with MDA-MB-231 cells neither melanoma cell line exhibited adhesive cell-cell interactions in suspension, regardless of ODAM expression." (PMID 23648148, 2013).
odontogenic tumors (2 papers, 2013 to 2022). "Tau amyloid is associated with ganglioglioma, IAPP with neuroendocrine tumors, the N-terminus of prolactin with pituitary adenoma and ODAM with odontogenic tumors." (PMID 36232958, 2022).
colorectal adenocarcinoma (1 paper, 2024). The most common type of colorectal carcinoma. "Odontogenic, Ameloblast-Associated (ODAM) is frequently upregulated in hepatocellular carcinoma, colorectal adenocarcinoma, and hepatoblastoma." (PMID 38572434, 2024).
craniopharyngioma (1 paper, 2024). A benign, partly cystic, epithelial tumor of the sellar region, presumably derived from Rathke pouch epithelium. "Ghost cells in adamantinomatous craniopharyngioma cases also exhibited strong ODAM expression." (PMID 39451638, 2024).
dental fluorosis (1 paper, 2022). A condition that results from excessive fluoride ingestion during tooth development, resulting in tooth discoloration ranging from white streaks to brown stains and cracks or pits in the tooth enamel. "The potential role of single nucleotide variants of ODAM, MMP20, and AMELX in the development of dental fluorosis was recently investigated using DNA sequencing." (PMID 36117697, 2022). "Results from this study indicated rs1514392 of ODAM, did not have a significant effect on the severity of dental fluorosis between populations, whilst rs1784418 of MMP20 was significantly associated with susceptibility to dental fluorosis." (PMID 36117697, 2022).
gingival fibromatosis (1 paper, 2015). "GEO data showed that ODAM expression decreased significantly in gingival tissues with hereditary gingival fibromatosis compared with those of normal patients." (PMID 25911094, 2015).
tumor (8 papers, 2013 to 2024). "This association should serve to clarify the clinical import of ODAM expression and any role it may serve as an indicator of tumor behavior." (PMID 23648148, 2013). "Further, in the basal lamina, the odontogenic ameloblast-associated protein (ODAM) is implicated in diverse activities such as ameloblast differentiation, junctional epithelial attachment to teeth enamel maturation, and tumor growth." (PMID 35137648, 2022). "The odontogenic ameloblast-associated protein (ODAM) has been implicated in diverse activities, such as ameloblast differentiation, enamel maturation, and tumor growth (7, –, 10)." (PMID 25911094, 2015). "This will hinge on further investigation into ODAM localization/functionality in the context of tumor cell variation." (PMID 23648148, 2013). "Our findings revealed similarities in AMELX and ODAM expression between these two tumor types, supporting the hypothesis of a shared embryological origin from the oral ectoderm." (PMID 39451638, 2024). "ODAM was subsequently characterized as the main protein constituent of a unique form of odontogenic amyloid found in calcifying epithelial odontogenic, or Pindborg, tumours." (PMID 36117697, 2022). "We found cytoplasmic and nuclear expression of ODAM in CAA tumor cells." (PMID 34493785, 2021). "Defining ODAM expression in relation to signaling pathways active across the range of tumor phenotypes will allow us to further clarify its role in tumorigenesis and delineate any relationship it may have to pathway-specific therapeutic intervention." (PMID 23648148, 2013). "It is postulated that the pathogenic role of ODAM in tumours might be related to its intracellular, rather than extracellular secreted form." (PMID 36117697, 2022). "All five clusters of tumor epithelial cells were indeed observed in AM samples by using marker genes (HLA-B for IR, SFRP1 for BR, KRT13 for ED, ODAM for TD, LAMC2 for TD, and KI67 for CC)." (PMID 38424060, 2024). "In addition, ODAM–transfected cells were assayed for signal transduction via AKT which promotes cell proliferation and survival in many neoplasms." (PMID 23648148, 2013).
cancer (3 papers, 2013 to 2022). A tumor composed of atypical neoplastic, often pleomorphic cells that invade other tissues. "ODAM is postulated to be an inhibitor of cancer onset and progression, whilst its potential as a therapeutic target and biomarker remains incompletely characterized." (PMID 36117697, 2022). "ODAM was also found to be overexpressed in several cancers of epithelial origin, such as gastric, breast, salivary gland, trachea, and colorectal cancers indicating its potential both as a biomarker for prognosis and therapeutic target." (PMID 36117697, 2022). "Bioinformatics and research data have identified the anti-cancer properties of ODAM, indicating its potential both as a prognostic biomarker and therapeutic target." (PMID 36117697, 2022).
epithelial neoplasm (2 papers, 2014 to 2024). A benign or malignant neoplasm that arises from and is composed of epithelial cells. "The elevated expression of ODAM in FAs provides a potentially novel insight to the pathogenesis of epithelial neoplasms, since ODAM is a developmental antigen with an essential role in tooth maturation and the pathogenesis of various epithelial neoplasms." (PMID 24781529, 2014). "Similarly, ODAM, a developmental antigen crucial for tooth maturation, plays a role in the pathogenesis of various odontogenic and epithelial neoplasms." (PMID 39451638, 2024).
genetic diseases (1 paper, 2019). "The overlap in naturally occurring gene inactivations and human genetic diseases suggests that ODAM may be linked to some dental or gingival deformities." (PMID 30674270, 2019).
infection (1 paper, 2022). The state of being infected such as from the introduction of a foreign agent such as serum, vaccine, antigenic substance or organism. "Surprisingly, ODAM was also highly expressed in prostate glands, which suggests that ODAM might be involved with the repair of prostate epithelial cells damaged by local infection and environmental factors, thereby playing a similar protective role as in the JE." (PMID 36117697, 2022).
ODAM also shares sentences with these, for which no sentence is quoted: Peri-Implantitis (2 papers); amelogenesis imperfecta (1); breast tumor (1); cardiovascular diseases (1); chronic periodontitis (1); dentin dysplasia (1); ganglioglioma (1); gastric cancer (1); hepatoblastoma (1); hepatocellular carcinoma (1); lung carcinoma (1); neuroendocrine tumors (1); pituitary adenoma (1); testicular cancer (1); type 2 diabetes (1).